BMI1 (BMI1 proto-oncogene, polycomb ring finger)
Diseases named in the same sentence as BMI1 in open-access papers (continued):
Sharing a sentence is not in itself a finding about the gene and the disease.
glioma (continued). "Furthermore, we found that DANCR acted as a ceRNA to regulate BMI1-mediated effects on progression of glioma via sponging miR-135a-5p." (PMID 32099526, 2020). "Indeed, dual inhibition of EZH2 and BMI1 has already been shown to have more pronounced effects in vitro and in vivo in glioma stem cells than either agent alone and in multiple myeloma." (PMID 31380371, 2019). "In glioma, the miR-128 targets BMI1 leading to reduced self-renewal capacity." (PMID 29401683, 2018). "Another study showed that high doses of radiation reduced miR-128 levels and increased Bmi-1 expression in glioma U87 cells, which may promote escape from radiation-induced cellular senescence and confer instead radioresistance." (PMID 29246031, 2017). "Furthermore, inhibition of uPAR and cathepsin B in glioma stem cells was associated with decreased expression of SOX2 and Bmi1, suggesting that cathepsin B and uPAR have pivotal roles in maintaining the malignant nature of CSCs in gliomas." (PMID 28611989, 2017). "A recent study suggested that miR-128-1 was downregulated in GBM and glioma stem-like cells (GSCs) and miR-128-1 could inhibit the growth of glioblastoma multiforme and glioma stem-like cells via targeting BMI1 and E2F3." (PMID 28947999, 2017). "Silencing NRF2 decreases the self-renewal capacity of glioma stem cells by critically reducing the expression of B lymphoma Mo-MLV insertion region 1 homolog (Bmi1, a transcription regulation factor for stem cells), SRY-box 2 (Sox2, a regulator of growth factors) and Cyclin E." (PMID 28671577, 2017). "Considering our previously established miR-218/Bmi1 pathway in glioma inhibition, we hypothesized that Bmi1 may fill the gap between miR-218 induced HK2 suppression." (PMID 29220380, 2017). "Previously we revealed the tumor suppressor function of miR-218, which could dramatically reduce the proliferation, migration, invasion and self-renewal of glioma cells, by targeting its functional downstream target Bmi1, a stem cell-promoting oncogene." (PMID 29220380, 2017). "Moreover, BMI-1 was shown to promote the angiogenic activity of glioma and hepatocellular carcinoma cells." (PMID 26935956, 2016). "We observed a significant increase in the self-renewing capacity, expression of stem cell markers, and proliferative capacity in glioma cells stably overexpressing COX4-1, suggesting that COX4-1 regulates glioma stem-like cells in part by regulating BMI1 expression." (PMID 25726526, 2015). "In addition, a significant direct correlation between the expression of COX4I1 and BMI1 was observed in human tissue from primary gliomas at the mRNA and protein levels." (PMID 25726526, 2015). "To gain insight into the mechanism by which COX4 isoform expression regulates tumor proliferation and phenotypic changes, we determined whether reduction of BMI1 levels affects the growth of glioma cells." (PMID 25726526, 2015). "BMI1 is essential for glioma proliferation and self-renewal." (PMID 25831237, 2015). "For these reasons, Bmi-1 presents an attractive target for glioma therapy." (PMID 25364434, 2014). "Combined, these data suggested that over-expression of BMI1 mRNA occurred in ~50% of pediatric brain tumors (compared with normal adult cerebral tissues), and pGBMs tend to have higher levels than that in the low-grade gliomas." (PMID 25526772, 2014). "Future studies focusing on the expression of Bmi-1 and its downstream genes, using gene transfection technology in additional glioma cell lines, may aid in determining the possible mechanism of Bmi-1 in the radioresistance of glioma cells." (PMID 25364434, 2014). "The Bmi-1 gene expression in embryonal and gliomas tumors was 3.59- and 5.54-fold, respectively." (PMID 23984324, 2013). "Our findings that Bmi-1 modulates the NF-κB/VEGF-C signaling pathway to mediate an angiogenesis phenotype in human gliomas further suggests that Bmi-1 may represent a prospective therapeutic target for anti-angiogenic strategies against the disease." (PMID 23383216, 2013).
glioma (continued). "Additionally, when compared with control gliomas, Bmi-1 overexpression up-regulated VEGF-C levels whereas knockdown of Bmi-1 resulted in decreased VEGF-C expression in brain gliomas." (PMID 23383216, 2013). "The transcription of Nestin, along with the transcription of two other genes that are important to nervous system development (Bmi-1 and Sox2), were used as markers of cell proliferation to evaluate the role of melatonin on glioma cell differentiation and proliferation." (PMID 24137328, 2013). "Additionally, HUVEC migration was markedly induced by CM of Bmi-1-overexpressing glioma cells compared with control CM." (PMID 23383216, 2013). "Toward an understanding of the mechanism by which Bmi-1 promotes the angiogenesis of glioma cells, we investigated whether Bmi-1 induces the expression VEGF-C in glioma cells." (PMID 23383216, 2013). "Additionally, compared to that in control cells, the activity of a VEGF-C promoter that contains a NF-κB binding site was significantly increased in Bmi-1-overexpressing but markedly decreased in Bmi-1-silenced glioma cells." (PMID 23383216, 2013). "Thus, our finding that Bmi-1 upregulates VEGF-C expression in glioma cells through NF-κB activation further underscores the importance of VEGF-C in glioma angiogenesis and provides a basis for using VEGF-C as a surveillance biomarker during anti-Bmi-1 therapy." (PMID 23383216, 2013). "It suggests that the Bmi-1 gene plays some roles in the progression of gliomas tumors." (PMID 23984324, 2013). "Our current study examined the effects of Bmi-1 on glioma angiogenesis in vitro as well as in vivo." (PMID 23383216, 2013). "Together, our data suggest that Bmi-1 plays an important role in glioma angiogenesis and therefore could represent a potential target for anti-angiogenic therapy against the disease." (PMID 23383216, 2013). "In addition, levels of secreted VEGF-C protein in the supernatants of Bmi-1-overexpressing glioma cells was also elevated." (PMID 23383216, 2013). "Notably, Bmi-1 and Sox2 were upregulated at therapeutic concentrations of melatonin in the glioma cell line." (PMID 24137328, 2013). "Additionally, ectopic expression of Bmi-1 by glioma cells also potently induced the formation of second- and third-order vessels in chicken chorioallantoic membranes (CAM assay)." (PMID 23383216, 2013). "Lastly, we examined whether Bmi-1 induced angiogenesis of glioma cells via activating NF-κB signaling." (PMID 23383216, 2013). "To assess whether Bmi-1-induced glioma angiogenesis in vivo, we utilized an orthotopic brain glioma tumor model and determined whether Bmi-1 modulates glioma angiogenesis in the brain." (PMID 23383216, 2013). "We have previously shown that Bmi-1 induces NF-κB activation in glioma cells." (PMID 23383216, 2013). "Furthermore, expression of Bmi-1 correlated with NF-kappaB nuclear translocation as well as MMP-9 expression in clinical glioma samples." (PMID 22967049, 2012). "The key finding of this study is that Bmi-1 may induce an aggressive phenotype in glioma via modulation of the NF-kappaB signaling." (PMID 22967049, 2012). "BMI-1 copy number variations have been observed in a subset of gliomas, and targeting BMI-1 by microRNA-128 could inhibit glioma proliferation." (PMID 22348397, 2012). "We previously reported that Bmi-1 promoted NF-kappaB activation in glioma." (PMID 22967049, 2012). "The increased migratory and invasive ability of Bmi-1-overexpressing glioma cells were dramatically reversed by treatment with JSH-23, a specific NF-kappaB inhibitor that reduces the transcriptional activity of NF-kappaB, and these effects were accompanied by a reduction in MMP-9 expression." (PMID 22967049, 2012). "Bmi-1 may therefore represent a potential therapeutic target for improved treatment of human gliomas." (PMID 22967049, 2012).
glioma (continued). "Furthermore, the Transwell matrix penetration assay (coated with Matrigel) showed that overexpression of Bmi-1 increased the invasive ability of both glioma cell lines." (PMID 22967049, 2012). "Targeting of the Bmi-1 in stem cells by microRNA-128 inhibits glioma proliferation and self-renewal, implying that miRNA-128 may be a therapeutic target agent for the "stem cell-like" characteristics of glioma." (PMID 22995409, 2012). "Next, we examined whether Bmi-1 increased the aggressiveness of glioma cells via activation of the NF-kappaB signaling pathway." (PMID 22967049, 2012). "Our current study indicates that Bmi-1 modulates the NF-kappaB/MMP-9 signaling pathway to mediate an aggressive phenotype in human glioma, suggesting that Bmi-1 may represent a potential therapeutic target for the treatment of glioma." (PMID 22967049, 2012). "Lastly, we examined whether the NF-kappaB-activating effect of Bmi-1 in glioma cells found in our in vitro tests was clinically relevant." (PMID 22967049, 2012). "Strikingly, the 3-D spheroid invasion assay demonstrated that Bmi-1-overexpressing glioma cells displayed cellular morphologies typical of a highly invasive phenotype, as the cells presented increased numbers of outward projections compared to the control cells." (PMID 22967049, 2012). "One other recent study of miR-128a in glioma also reported that Bmi-1 is a target for miR-128a." (PMID 20574517, 2010). "Furthermore, it was shown recently that microRNA-128 inhibits proliferation and self-renewal in glioma at least partially by downregulating Bmi1." (PMID 19823589, 2009). "Interestingly, the promotion of Bmi‐1 migration and invasion by glioma cells is probably mediated by the regulation of p16, a protein that can suppress the proliferation and self‐renewal of glioma cells." (PMID 39791545, 2025). "Interestingly, long noncoding RNAs (lncRNAs) such as DANCR and LINC00152 sponged miR‐135a‐5p and miR‐16, respectively, to reverse the inhibitory effects on glioma progression by promoting Bmi‐1 expression and Bmi‐1‐mediated effects on glioma cell proliferation and invasion." (PMID 39791545, 2025). "Expression of Bmi-1 could protect glioma cells from apoptosis by activating the NF-κB pathway." (PMID 35897796, 2022). "Moreover, miR-135a-5p could specially bind to BMI1, and the expression of BMI1 was obviously elevated in glioma tissues and cells." (PMID 32099526, 2020). "But the potential role and mechanism of BMI1 related to the development of glioma remain unclear." (PMID 32099526, 2020). "Notably, the gene for BMI1 is aberrant at the chromosomal level in gliomas, contributing to the pathogenesis of tumors; BMI1 might also initiate cells that promote the undifferentiated state of GBM cells." (PMID 30658672, 2019). "Therefore, targeting Bmi-1 may provide therapeutic benefits to glioma patients undergoing radiotherapy." (PMID 29246031, 2017). "The ability of CAR to interfere with Nanog, Oct4, SOX2, CD44 and BMI1 expression is consistent with the effects of other natural compounds (e.g., adriamycin and diflourinated curcumin) to control the cancer stem cell bulk and the aggressiveness of glioma and pancreatic adenocarcinoma." (PMID 29123181, 2017). "However, little is known about how BMI1 is regulated in glioma cells." (PMID 25726526, 2015). "Notably, mice bearing COX4-1-expressing glioma cell xenografts quickly developed invasive tumors characterized by the presence of multiple lesions positive for Ki-67, BMI1, and COX4-1, whereas mice bearing COX4-2-expressing xenografts rarely developed tumors by this point." (PMID 25726526, 2015). "As Bmi-1 is also known to promote the stem cell renewal, a process that is important in glioma, hence miRNA-128 may be used against the "stem cell-like" characteristics of glioma cells." (PMID 24555688, 2014).
glioma (continued). "In summary, we identified the over-expressed BMI1 as a promising therapeutic target for glioma stem cells, and suggest that the signaling pathways associated with activated BMI1 in promoting tumor growth may be different from those induced by silencing BMI1 in blocking tumor formation." (PMID 25526772, 2014). "In addition, Bmi-1 may be significant in increasing the radioresistance of glioma cells by enabling cell senescence." (PMID 25364434, 2014). "Although the total number of pediatric gliomas that over-expressed BMI1 mRNA varied depending on the normal references (fetal brain vs. adult brain), the trend remained the same, i.e. high-grade gliomas expressed higher levels of BMI1 mRNA than did low-grade gliomas." (PMID 25526772, 2014). "Therefore, clinically, the measurement of the Bmi-1 gene expression could be helpful in diagnosis of gliomas from embryonal tumors." (PMID 23984324, 2013). "Furthermore, MMP-9 and IL-8 expression are further increased in Bmi-1-overexpressing glioma cells." (PMID 23383216, 2013). "Whether Bmi-1 has a biological function in glioma angiogenesis however, remains unclear." (PMID 23383216, 2013). "Furthermore, JSH-23 treatment also attenuated Bmi-1 induction of VEGF-C expression in glioma cells." (PMID 23383216, 2013). "Thus, targeting GSC-promoting microenvironment cytokines or interference with Bmi-1 may be essential for a higher efficacy of glioma therapies." (PMID 22330721, 2012). "Moreover, the invasivenes of Bmi-1-overexpressing glioma cells could be abrogated by an MMP-9 inhibitor, suggesting that MMP-9 played an important role in mediating Bmi-1-induced invasion of glioma cells." (PMID 22967049, 2012). "In addition, miR-128 has been reported to target BMI-1 in glioma." (PMID 21851624, 2011). "Immunocytochemistry showed that Sox2 and Bmi1, which are necessary for the normal functioning of both embryonic stem cells and neural stem cells, were expressed by a majority of cells in the low- and high-grade gliomas cultures studied (10/10 and 6/6 cultures, respectively)." (PMID 21297991, 2011). "In addition, BMI1 copy number alteration is frequent in human gliomas." (PMID 20920292, 2010). "Moreover, glioma cells that stably overexpress SOD and CAT exhibit high resistance to TMZ, enhanced tumorsphere formation, and poor prognosis, and TMZ-resistant glioma cells display increased expression of CAT, SOD2, and BMI1, a protein associated with stemness and therapy resistance." (PMID 40298811, 2025). "We demonstrated that CNIH4 has a significant effect on GSC markers (CD144, CD44, and BMI1) via knocking down CNIH4 by using specific shRNAs, implying that CNIH4 as a definite therapeutic target in glioma stem cells." (PMID 37062068, 2023). "Treatment of glioma cells with OPC-derived conditioned medium significantly increased the expression of typical stemness genes (e.g., Nanog, Sox2, Oct3/4, and Bmi1), sphere-forming ability, and cell viability of glioma cells and promoted chemo-radioresistance." (PMID 38020906, 2023). "In glioma cell cultures, silencing of uPAR and cathepsin B downregulates the expression of CD133, Nestin, Sox2 and Bmi1 and reduces the number of glioma-initiating cells." (PMID 35493073, 2022). "miR-128-3p is known to regulate drug resistance by targeting various genes, including c-Met, MUC1-C, BMI-1, and ABCC5 in hepatocellular carcinoma, glioma, lung cancer, and ovarian cancer." (PMID 36672566, 2022). "ANGPTL4 overexpression can induce the GSCs enrichment, which is characterized by the expression of polycomb complex proteins BMI-1 and SOX2, contributing to the resistance of glioma cells to temozolomide." (PMID 36247876, 2022). "It was established that BMI1 and EZH2 secretion in glioma tissues were expressively elevated compared to those in nonneoplastic brain tissues." (PMID 34745848, 2021).
glioma (continued). "Studies have shown that BMI1 was capable of modulating tumor induction and growth in a genetically engineered murine model of GBM as well as human stem-like glioma lines." (PMID 34745848, 2021). "Our previous studies also revealed increased expression of CAT, superoxide dismutase 2 (SOD2), and BMI1, a protein related to stemness and therapy resistance, in TMZ-resistant glioma cells." (PMID 34943091, 2021). "Bmi1 is highly expressed in glioblastoma stem/initiating cells (GIC) and microRNAs—miR128 and miR218—have been identified, which specifically block glioma self-renewal through Bmi1-downregulation." (PMID 31988455, 2020). "The treatment of glioma cells with cyclopamine, GANT61 or siRNA against GLI1, GLI2, or GLI3 significantly decreased the expression of GLI1, FOXM1, BMI1, SOX2, and OCT4, involving in the maintenance of the stem cell state." (PMID 30730955, 2019). "Up-regulation of cathepsin B and uPA receptors induces SOX2 and Bmi1 expression, both critical for maintaining the stemness of glioma CSCs, while knockdown of cathepsin B and uPA receptors suppresses expression of SOX2, Bmi1 and nestin, in vivo." (PMID 31683669, 2019). "The expression patterns of other glioma stem cell promoting proteins that were found in the list of deregulated genes, ITGA6 and BMI1, where variable." (PMID 29724193, 2018). "“If HK2 is a direct functional downstream target of Bmi1” was not assessed, though a direct correlation was established between Bmi1 and HK2 expression in glioma cells." (PMID 29220380, 2017). "Research has shown that some stemness markers such as L1CAM (CD171), Bmi-1, SOX2, and CD44 can also regulate glioma radioresistance." (PMID 29246031, 2017). "Accordingly, miR128-1 overexpression resulted in reduced expression of both BMI1 and E2F3 in glioma cells and GSCs." (PMID 27705931, 2016). "In both in vitro and in vivo studies, it was found that endothelial cells, when cocultured with glioma cells, promoted the phenotype of CSC-like glioma cells, increasing the expression genes such as Sox2, Olig2, Bmi1, and CD133 and their tumorigenicity." (PMID 26880981, 2016). "BMI1, a component of the PRC2 polycomb repressor complex, has emerged as the most important player for the self-renewal and malignant transformation of glioma." (PMID 27705931, 2016). "BMI1 stimulates glioma through an INK4A/ARF-independent pathway and the same situation also applies to BMI1/Ras-elicited hepatic carcinogenesis." (PMID 26633535, 2015). "The down-regulation of miR-128ab in human glioma and glioblastoma cell lines has previously been reported to increase the expression of ARP5, Bmi-1 and E2F-3a, promoting neural stem cells renewal and regulate cell-cycle progression." (PMID 23358700, 2013). "ELISA and the gelatin zymography assay confirmed that overexpression of Bmi-1 increased MMP-9 expression and activity in glioma cells." (PMID 22967049, 2012). "Knockdown of Bmi-1 also significantly decreased the expression and activity of MMP-9 in glioma cells when compared with vector-control cells." (PMID 22967049, 2012). "In the current study, we assessed the impact of Bmi-1 on NF-kappaB transcriptional activity in A172 and LN229 glioma cells using a luciferase reporter assay." (PMID 22967049, 2012). "Taken together, these data suggested that overexpression of Bmi-1 upregulated and activated MMP-9 in glioma cells in vitro." (PMID 22967049, 2012). "To understand the mechanism by which overexpression of Bmi-1 promoted the invasiveness and migration of glioma cells, we investigated the expression and activity of MMP-9 in A172 and LN229 glioma cells stably overexpressing Bmi-1." (PMID 22967049, 2012).